LEF1 (lymphoid enhancer binding factor 1)
Diseases named in the same sentence as LEF1 in open-access papers (continued):
Sharing a sentence is not in itself a finding about the gene and the disease.
colorectal cancer (continued). "To investigate the localisation of LEF-1 and TCF4 in human colorectal cancer, we evaluated the expression of these proteins by immunostaining on tissue microarrays." (PMID 21092222, 2010). "This study demonstrates different prognostic values of LEF-1 and TCF4 expression in colorectal cancer patients indicating different regulation of these transcription mediators during tumour progression." (PMID 21092222, 2010). "In this study we investigated the expression of β-Catenin, LEF1 and TCF4 in colorectal carcinomas and their prognostic significance." (PMID 21092222, 2010). "LEF-1 expression was found in 56 (26%) and TCF4 expression in 99 (46%) of colorectal carcinomas and both were heterogenously distributed throughout the tumours." (PMID 21092222, 2010). "Indeed, several studies have shown that LEF1 silencing attenuates cancer proliferation and induces apoptosis in glioblastoma multiforme (GBM) and colorectal cancer." (PMID 32933177, 2020). "In colorectal cancer the expression of TCF4 as well as LEF-1 has been described, but was not accurately evaluated and compared with nuclear β-catenin positivity." (PMID 21092222, 2010). "LEF-1 expression does not correlate with age, gender or T-category of the investigated colorectal cancer cases." (PMID 21092222, 2010). "In contrast LEF-1 expression was found only in 26% and TCF4 in 46% of colorectal carcinomas." (PMID 21092222, 2010). "Roles for LEF/TCF proteins has been studied in tissue-culture and animal models of intestinal stem cells and colorectal cancer, which suggested roles for TCF7L2 and TCF7 in normal colorectal tissue, where LEF1 and TCF7L1 are silent, but strong expression in colorectal tumor of LEF1 and TCF7." (PMID 32403323, 2020). "As LEF-1 is not expressed in the normal colon mucosa, but is found in human colorectal cancer, a shift of β-catenin binding partners from TCF4 to LEF-1 might occur during carcinogenesis which might enable enhanced epithelial-mesenchymal transition (EMT) and malignant progression." (PMID 21092222, 2010). "The present study establishes that the nuclear expressions of TCF4, LEF-1 and β-catenin do not correlate with each other and that TCF4 and LEF-1 positivity is not mutually exclusive in colorectal cancer." (PMID 21092222, 2010). "In our meta-analysis, NFE2L2 is noticeable for the large discrepancy between positive correlation with LEF1 and negative correlation with TCF7L1, which clearly substantiates the importance of NFE2L2 as an important WNT/β-catenin target gene in human colorectal cancer." (PMID 32403323, 2020).
colon carcinoma (37 papers, 2009 to 2025). "MYC activates the transcription of LEF1 and is required for LEF1 expression in colon cancer cells and in primary colonic cells transformed by APC loss of function, a common mutation in colon cancer patients." (PMID 31623618, 2019). "Knocking down MYC or LEF1 caused a dramatic reduction in the viability of the colon cancer cells DLD1 and RKO." (PMID 31623618, 2019). "The main binding partner of β-catenin in the colon is TCF4, but colon tumors isolated from APC mutated mice have an increased expression of LEF1 and TCF1." (PMID 29975781, 2018). "We found that levels of LEF1 mRNA and protein were significantly increased in colon cancer tissues and associated with infiltration depth, lymph node and distant metastases and shorter overall survival." (PMID 24098538, 2013). "Indeed, LEF1 knockdown was previously shown to cause a reduction in colon cancer cell growth in vitro and when xenotransplanted into immune-deficient mice." (PMID 31623618, 2019). "The role of LEF1 is controversial, usually detected and upregulated in most colonic carcinomas, enhancing the progression." (PMID 39200196, 2024). "These findingssupport previous reports on the LEF1 function in cancer malignancy:In colon cancer, for example, knockdown of LEF1 reduced cellviability, invasion capacity, and proliferation through cell cycle stabilization." (PMID 38100720, 2023). "Altered LEF1 expression and function commonly occur in several cancers, such as lung adenocarcinoma, colon cancer, endometrial carcinoma, prostate cancer, and leukemia." (PMID 38003292, 2023). "Cyclin D1 and LEF-1 (Lymphoid Enhancer Binding Factor 1) are overexpressed in colon cancer and have been identified as the target genes of miR-449a in human prostate cancer and mesenchymal stem cells." (PMID 34737955, 2021). "It has been demonstrated that miR-26b expression is a potent inhibitor of colon cancer cell proliferation and significantly decreases LEF1 expression." (PMID 34062897, 2021). "Normal human colon cells express low levels of LEF1 and high levels of miR-26b, while human colon cancer cells have a decreased miR-26b expression and an increased LEF1 expression." (PMID 34062897, 2021). "We also searched the GEO database and found that the DHRS2 gene is upregulated in colon cancer cells treated with the adenoviral LEF1 expression vector (GEO accession number: GSE3229), which is consistent with our results." (PMID 32586085, 2020). "Bioinformatic analyses were utilized to define the expression of MYC-regulated genes in human colon cancer and metabolomics analyses were used to identify pathways regulated by LEF1 in MYC expressing cells." (PMID 31623618, 2019). "Nuclear and cytoplasmic fractionation experiments followed by Western blotting, confirmed that silencing LEF1 reduced the nuclear pool of β-catenin in the established colon cancer cell line DLD1 and in HCEC-APC." (PMID 31623618, 2019). "MYC knockdown reduced LEF1 mRNA expression in DLD1 cells, thus indicating that LEF1 is transcriptionally regulated by MYC in colon cancer." (PMID 31623618, 2019). "Positive autoregulation has been described before for LEF1 in colon cancer, XTcf-4 (Tcf7l2) in Xenopus midbrain and zebrafish Tcf3 (Tcf7l1)." (PMID 29942461, 2018). "In colon cancer cells, beta-catenin/LEF1 complexes drive transcription of the full-length LEF1 isoform that can bind beta-catenin at the expense of a dominant negative isoform." (PMID 26509276, 2015). "Direct binding of Lef1/Tcf transcription factors to the Lef1 promoter was shown in colon cancer/lymphocytes as well as in HEK 293 cells, which is in accordance with our prediction." (PMID 25145340, 2014). "Taken together, LEF1 protein was overexpressed in colon cancer tissues and knockdown of LEF1 expression inhibited colon cancer growth in vitro and in vivo." (PMID 24098538, 2013). "To further understand the role of LEF-1 in colon cancer, we knocked down LEF1 expression in two colon cancer cell lines, SW480 and SW620." (PMID 24098538, 2013).
colon carcinoma (continued). "In this study, we first determined expression of LEF1 protein in human colon cancer tissues and cell lines using immunohistochemistry." (PMID 24098538, 2013). "After that, we determined the effect of LEF1 knockdown on the regulation of colon cancer cell invasion using the Matrigel invasion assay." (PMID 24098538, 2013). "The tumor weight also showed that knockdown of LEF1 expression inhibited the growth of colon cancer cells in nude mice, because the weight of tumors mass in SW480 and SW620 cells expressing shLEF1 was significantly lighter than those in the control mice." (PMID 24098538, 2013). "Altered expression of LEF1 protein has been reported to be involved in tumorigenesis of different human cancers, including colon cancer." (PMID 24098538, 2013). "The results showed that 71 of 106 colon tissues and 23 of 106 paratumours normal colon tissues expressed the LEF1 protein, indicating that colon cancer tissues expressed higher levels of LEF1 than those in the paratumours normal colon tissues (P<0.05)." (PMID 24098538, 2013). "Obviously, LEF1 expression was observed in the nuclei in colon cancer tissues and paratumours normal colon tissues." (PMID 24098538, 2013). "A total of 106 colon cancer and matched paratumorous normal tissues were used to assess LEF1 expression using immunohistochemistry and qRT-PCR." (PMID 24098538, 2013). "Further studies will verify LEF1 as a biomarker for the prediction of colon cancer progression and survival of patients." (PMID 24098538, 2013). "To explore the role of LEF1 on colon cancer cells, we utilized a lentivirus carrying LEF1 shRNA to infect SW480 and SW620 for knockdown of LEF1 expression." (PMID 24098538, 2013). "Thereafter, we will evaluate LEF1 as a promising therapeutic target for the prevention and therapy of colon cancer." (PMID 24098538, 2013). "The aim of this study was to evaluate the effect of the different LEF-1 phenotypes on the growth of colon carcinoma cell lines." (PMID 22639890, 2012). "The role of different isoforms of LEF-1 on the growth of human colon carcinoma cell lines (SW480 and HT-29) was studied using various in vitro and in vivo assays." (PMID 22639890, 2012). "Although it has been suggested that different isoforms of the lymphoid enhancer factor (LEF-1) have opposing biological activities, the biological outcome of aberrant LEF-1 activation in colon cancer is still unclear." (PMID 22639890, 2012). "Lef1 is ectopically expressed in colon cancer by the preferential targeting of a full-length (FL), ß-catenin-sensitive Lef1 isoform by activated ß-catenin and TCF transcription complexes." (PMID 22792274, 2012). "In vivo, the colon cells expressing LEF-1-ΔL slowed the growth of colon tumors, and neo-angiogenesis was decreased notably." (PMID 22639890, 2012). "In contrast to what has been observed in colon cancer, the uterus normally expresses Lef1 protein both during its initial development and as it cycles through estrus." (PMID 22792274, 2012). "Lymphoid enhancer factor 1 (LEF-1) is a member of the high mobility group box family that has important roles in organogenesis and colon cancer progression." (PMID 22639890, 2012). "If Groucho uses a co-recruited HDAC activity to oppose β-catenin•LEF-1, is this action sufficient to counter endogenous β-catenin and its recruited histone acetyltransferase complexes in colon cancer cells?" (PMID 19460168, 2009). "In this study, HT-29 colon cancer cells with truncated APC have LEF-1/β-catenin complexes constitutively occupying a WRE in the cMYC enhancer." (PMID 19460168, 2009). "Myc controls the expression of LEF1 to activate the Wnt pathway in colon cancer." (PMID 39200196, 2024). "Moreover, studies on human colon cancer cells have shown that MYC activates the expression of LEF1, thus promoting cell proliferation, and that LEF1 also plays a pivotal role in regulating lineage differentiation in pluripotent stem cells." (PMID 38474345, 2024).
colon carcinoma (continued). "Therefore, we stably transfected LEF1 and its mutants, respectively, in HCT116 cells, a colon cancer cell line expressing low levels of LEF1, to investigate the role of LEF1 LLPS in tumor proliferation and migration." (PMID 37657935, 2023). "Myc induces the expression of LEF1 to activate the Wnt pathway in colon cancer." (PMID 34639214, 2021). "We have shown that miR-26b directly targets Lef-1 and represses colon cancer cell proliferation." (PMID 32760291, 2020). "Knocking down MYC reduced LEF1 protein in colon cancer cells such as RKO and DLD1." (PMID 31623618, 2019). "To determine whether LEF1 expression is necessary to maintain the nuclear pool of β-catenin in colon cancer cells, we silenced LEF1 in DLD1 cells and in HCEC partially transformed by truncated APC." (PMID 31623618, 2019). "Because the activity of both MYC and the WNT pathway are profoundly involved in colon cancer, we examined the 41 pairs of normal/tumor colonic tissues deposited in the TCGA database for the expression of LEF1 and other genes upregulated by MYC in our RNA-seq dataset." (PMID 31623618, 2019). "However, the levels of LEF1 mRNA and protein are significantly greater in human colon cancer tissues, and LEF1 knockdown in xenograft models suppresses tumor formation and growth." (PMID 31623618, 2019). "Hence, our results suggest that MYC-dependent colon cancer cell are specifically sensitive to reduction in LEF1 expression." (PMID 31623618, 2019). "However, β-catenin and RAC1 were observed to interact with the TCF7 or LEF1 promoter region in both breast and colon cancer cells." (PMID 30650643, 2019). "In addition, serial sections of a primary human colon tumor stained with pPDH and LEF‐1 antisera show a striking concordance in expression pattern." (PMID 28183841, 2017). "We further explored the role of LEF1 in the growth of colon cancer." (PMID 24098538, 2013). "Similarly, real-time PCR analysis showed that levels of LEF1 mRNA were significantly increased in these 106 pairs of colon cancer tissues compared to the paratumours normal colon tissues (P<0.05)." (PMID 24098538, 2013). "Indeed, our current study analysed the expression of LEF1 mRNA and protein in colon cancer and paratumorous colon tissues and found that LEF1 was overexpressed in colon cancer tissues." (PMID 24098538, 2013). "This study aimed to assess LEF1 expression in colon cancer tissues and to explore changed phenotypes, gene expressions, and the possible mechanism after knocked down LEF1 expression in colon cancer cell lines." (PMID 24098538, 2013). "The levels of LEF1 expression were associated with infiltration depth, lymph node, and distant metastases, and advanced TNM stages of colon cancers as well as poor overall survival rate in patients with colon cancer." (PMID 24098538, 2013). "However, our current study is just proof-of-principle and much more needs to be done to clarify the function and role of LEF1 in colon cancer development and progression." (PMID 24098538, 2013). "The survival analysis (5-year follow-up of 106 colon cancer patients) showed that the median survival rate of patients with LEF1 expressed tumor was 48.5 months, which was significantly poorer than those with LEF1-negative tumors (more than 60 months) (P<0.05)." (PMID 24098538, 2013). "Moreover, expression of LEF1 protein was associated with infiltration depth, lymph node and distant metastases, and advanced TNM (tumor-node-metastasis) stages of colon cancer (P<0.01)." (PMID 24098538, 2013). "The tumor weight also indicated that LEF-1-ΔL inhibited the growth of colon carcinomas." (PMID 22639890, 2012). "To determine whether the expression of LEF-1 is frequent and thus a reliable marker of primary colon carcinoma, we first examined LEF-1 expression in colon tumor tissues and different cell lines." (PMID 22639890, 2012). "A deeper understanding of these processes might improve the targeted therapies for colon cancer by regulating the expression of LEF-1." (PMID 22639890, 2012).
colon carcinoma (continued). "Interestingly, in many colon cancer cell lines, only the LEF-1-FL protein is expressed strongly, and the expression of the short isoform is inhibited significantly." (PMID 22639890, 2012). "Overexpression of LEF-1-ΔL might be a promising candidate for treatment of colon cancer by sensitizing it to chemotherapeutic drugs." (PMID 22639890, 2012). "To determine whether the LEF-1 gene is involved in the development of colon cancers, we searched the expression state of the LEF-1 gene in colon carcinomas and cell lines." (PMID 22639890, 2012). "Enhanced expression of LEF-1-FL, which occurs frequently in colon cancer, may be a new target for clinical therapy." (PMID 22639890, 2012). "Similarly, GSEA of RNAseq data from a recent study of isogenic human colon cancer cells with wild‐type or oncogenic missense mutant FBXW7 (FBXW7R505C) identified LEF1 signalling as the most enriched gene set in FBXW7R505C cells, supporting a causal relationship." (PMID 37589076, 2023). "Furthermore, LEF1 expression was highly expressed in colon cancer cell lines SW480 and SW620." (PMID 24098538, 2013). "LEF-1, acting as a central transcription mediator of Wnt signaling and regulator of cell cycle- and growth-relevant genes, can be thought of as a target for clinical treatment and may provide a new direction for the therapy of colon cancer." (PMID 22639890, 2012). "MYC, LEF1, KLF4, SALL4, and IRF4 were the five important TFs involved in the regulation of the immune response in colon cancer." (PMID 34938284, 2021). "LEF1 was also necessary for maximum expression of PPARδ and ACAD9 in the fully transformed DLD1 colon cancer cells." (PMID 31623618, 2019). "Our results demonstrate that increased LEF1 expression by MYC led to the retention of β-catenin in the nucleus of normal and colon cancer cells." (PMID 31623618, 2019). "The expression of MYC, LEF1, PPARδ, and ACAD9 were closely correlated in a Western blot comparing colon cancer and normal adjacent benign tissue of human samples." (PMID 31623618, 2019). "In primary human patient colon tumors, our analysis revealed clear and striking heterogeneity in PDK activity and LEF‐1 expression in the epithelial portion of the tumor." (PMID 28183841, 2017). "For example, LEF-1 over-expression alone is sufficient to induce EMT in a developmental context, but both LEF-1 over-expression and APC truncation are required to induce EMT in a colon cancer setting." (PMID 27196929, 2016). "The c-myc gene has been identified as a direct target of LEF-1/TCF proteins, which are repressed by wild-type APC and activated by β-catenin in colon cancer cells." (PMID 26219398, 2015). "LEF1 knockdown reduced tumor cell viability, invasion capacity, and expression of MMP2 and MMP-9, but induced apoptosis in colon cancer cells." (PMID 24098538, 2013). "Furthermore, our current study showed that LEF1 overexpression in the primary CRC tissues was associated with distant metastasis of CRC patients, which is consistent with several previous studies documenting that LEF1 was characterized as a biomarker for colon cancer to metastasize to the liver." (PMID 24098538, 2013). "To disclose the possible convergent points and to clarify the potential mechanism by which LEF1 regulates proliferation and tumorigenesis, we detected the expression of Notch intracellular domain (NICD)/RBP-jκ/Hes1 pathway genes in these colon cancer cells." (PMID 24098538, 2013). "To understand LEF-1 function in colon cancer, we employed two colon cell lines, SW480 and HT29, to construct stable cell lines expressing each of two LEF-1 isoforms." (PMID 22639890, 2012). "In the evaluated 20 colon cancer cell lines, all but one (UBE3A) gene promoters were hypermethylated with frequencies ranging from 20% (LEF1 and MEF2C) to 100% (CNRIP1)." (PMID 21777459, 2011). "AXIN2, LEF1, TCF7, and PROX1 were highly expressed in colon cancer compared with control samples." (PMID 37584250, 2023).